MINAR1 (membrane integral NOTCH2 associated receptor 1)
Description:
Intrinsically disordered protein which may negatively regulate mTOR signaling pathway by stabilizing the mTOR complex component DEPTOR. Negatively regulates angiogenesis. Negatively regulates cell growth. Negatively regulates neurite outgrowth in hippocampal neurons (By similarity).
Synonyms: KIAA1024; UBTOR
Tractability: Antibody: UniProt places it where antibodies can reach, with high confidence; its Gene Ontology location is reachable by antibodies, with high confidence; UniProt predicts a signal peptide or a membrane-spanning region.
Gene: Protein-coding gene on chromosome 15 (79,431,003 to 79,472,304, forward strand). Ensembl gene ENSG00000169330.
Subcellular location: Cell membrane
Subcellular location (Human Protein Atlas): Golgi apparatus
Gene Ontology:
Molecular function: protein binding
Biological process: negative regulation of angiogenesis; negative regulation of cell growth; negative regulation of cell population proliferation; negative regulation of protein ubiquitination; negative regulation of TOR signaling; negative regulation of neuron projection development
Cellular component: plasma membrane
Genetic constraint (gnomAD): Loss-of-function variants: 40 observed, 68.31 expected, observed/expected ratio (o/e) 0.59, 90% interval 0.45 to 0.76. The upper end of that interval is the gene's LOEUF score, 0.76, which puts it in group 3 of 6, group 1 being the genes least tolerant of losing a copy. Missense variants: 1,128 observed, 1,209.6 expected, observed/expected ratio (o/e) 0.93, 90% interval 0.89 to 0.98. Synonymous variants: 482 observed, 474.63 expected, observed/expected ratio (o/e) 1.02, 90% interval 0.94 to 1.1.
Homologues: Orthologues: chimpanzee MINAR1 (99% identical), macaque MINAR1 (92% identical), pig MINAR1 (92% identical), mouse Minar1 (90% identical), rat Minar1 (90% identical), dog MINAR1 (89% identical), rabbit MINAR1 (88% identical), guinea pig MINAR1 (84% identical), tropical clawed frog minar1 (55% identical), zebrafish minar1 (53% identical), zebrafish si:dkey-88e18.8 (23% identical). Paralogues in human: MINAR2 (7% identical).
Diseases named in the same sentence as MINAR1 in open-access papers:
MINAR1 is named in the same sentence as 17 diseases in open-access papers, as found by Europe PMC text mining. Sharing a sentence is not in itself a finding about the gene and the disease. The quoted sentences say what the papers report.
breast carcinoma (3 papers, 2021 to 2026). "Major Innate Disordered Notch2-Associated Receptor 1 (MINAR1) is known to suppress angiogenesis and breast cancer cell growth and is associated with neurological disorders such as epilepsy." (PMID 41640244, 2026). "It has also been shown that Ubtor/MINAR1 plays a role in angiogenesis and breast cancer." (PMID 36317962, 2022). "It has also been shown that Ubtor/MINAR1 plays roles in angiogenesis and breast cancer." (PMID 34309811, 2021).
epilepsy (2 papers, 2020 to 2026). A brain disorder characterized by episodes of abnormally increased neuronal discharge resulting in transient episodes of sensory or motor neurological dysfunction, or psychic dysfunction. "In two siblings with intellectual disability, psychomotor retardation, blindness, epilepsy, movement disorder and cerebellar atrophy we identified rare homozygous variants in the genes LTBP1, EMILIN1, CACNB4, MINAR1, DHX38 and MYO15 by whole-exome sequencing." (PMID 32176688, 2020). "Collectively, our results establish MINAR1 as a key regulator of seizure susceptibility, likely via Gαs-cAMP-dependent modulation of SST+ interneurons, offering a molecular framework for developing targeted epilepsy therapies." (PMID 41640244, 2026).
Intellectual disability (2 papers, 2020 to 2021). "However, KIAA1024/MINAR1/UBTOR has not been reported as candidate gene for intellectual disability in large whole-exome sequencing studies." (PMID 32176688, 2020).
neurological diseases (2 papers, 2021 to 2026). "Our previous studies showed that UBTOR/KIAA1024/MINAR1 acts as a negative regulator of mTOR signaling, but whether UBTOR plays a role in neurological diseases remains largely unknown." (PMID 34309811, 2021).
MINAR1 also shares sentences with these, for which no sentence is quoted: cancer (2 papers); adrenocortical adenoma (1); adrenocortical cancer (1); Blindness (1); Cerebellar atrophy (1); glioblastoma (1); glioma (1); movement disorder (1); neurodevelopmental disorder (1); paraganglioma (1); pheochromocytoma (1); Seizure (1); tumor (1).